PTN (pleiotrophin)
Diseases named in the same sentence as PTN in open-access papers (continued):
Sharing a sentence is not in itself a finding about the gene and the disease.
cancer (continued). "For example, PTN (pleiotrophin) and MDK (midkine) are homologous ligands known to increase in response to inflammation and reported to influence many aspects of cancer biology, which are transcriptionally responsive to NF-κB." (PMID 36134665, 2022). "Pleiotrophin (PTN) is a potent cytokine that plays an important role in neural generation, angiogenesis, inflammation, and cancers." (PMID 35053198, 2021). "Protein tyrosine phosphatase receptor type S (PTPRS) was highly expressed in OV cancer cells and correlated with MYC/E2F targets, indicating that pleiotrophin (PTN) was secreted by fibroblasts binding to its receptor to promote the cancer cell growth." (PMID 34676217, 2021). "Other signature genes, including PTN, KLK4, RGMA and PIGR, have also been reported to be involved in cancer progression." (PMID 29642861, 2018). "We compared the expression of PTN and PTPRZ1 between normal breast and cancer tissues as well as before and after chemotherapy in cancer tissue using the microarray analysis data from the GEPIA database and GEO database." (PMID 30497491, 2018). "It was shown that MAP3K14, PTN, ACVR1 and HCK sharing different DNA methylation and gene expression across cancers were relatively high degree distribution in PPI network." (PMID 25774687, 2015). "ALK is activated by its ligands, midkine (MDK) and pleiotrophin (PTN), both of which serve as mitogenic and angiogenic factors in cancer." (PMID 24163262, 2013). "In this series at least one of the PTN–ALK pathway genes showed a significant correlation between high expression level and poor outcome for each of the cancers represented." (PMID 23267434, 2012). "To assess expression of the PTN–ALK pathway genes in stromal tissues, we analyzed several data sets from microdissection and transcriptome analysis of cancer and normal stroma." (PMID 23267434, 2012). "Pleiotrophin (PTN) is a developmentally-regulated growth factor which is widely distributed in various tissues and also detected in many kinds of carcinomas." (PMID 22496782, 2012). "PTN, also named heparin affinity regulatory peptide (HARP) in some studies, is a potent angiogenic factor, which stimulates proliferation and migration of endothelial cells during normal development and in cancer." (PMID 40904345, 2025). "Notably, high-PIMS cancer cells contributed more to outgoing communication than low-PIMS cells, particularly in the PTN and ANGPTL pathway networks." (PMID 40221501, 2025). "In cancer cells that do not express ανβ3 integrin, hypoxia or chemical hypoxia inhibits PTN expression in a HIF-1α-, HIF-2α-, and AP-1-independent manner." (PMID 40361445, 2025). "Moreover, luteolin decreased the pleiotrophin (PTN) expression, a gene positively related to cancer progression." (PMID 32521759, 2020). "Pleiotrophin (PTN) can interact with neuropilin-1 receptors, stimulating downstream signaling pathways, such as PI3K and focal adhesion kinase (FAK), to facilitate cancer growth and metastasis." (PMID 33066509, 2020). "Therefore, PTN promotes OS resistance to DOX treatment, a conclusion that accords somewhat with previous studies regarding the function of PTN in other cancer types." (PMID 28969035, 2017). "Targeting of the PTN/MK–ALK signaling pathway may provide a new, mechanism-based approach to the treatment of cancers that show activation of the pathway either due to high expression levels of either these molecules or less well defined mechanisms." (PMID 23267434, 2012). "These endothelial cells promoted cancer cell proliferation by secreting platelet-derived growth factor subunit B (PDGFB), which was stimulated by cancer cell-secreted vascular endothelial growth factor (VEGF), fibroblast growth factor 12 (FGF12), pleiotrophin (PTN) and neurofibromin 1 (NF1)." (PMID 24977105, 2012).
cancer (continued). "An analysis of 18 published gene expression data sets from different cancers shows that overexpression of ALK, its smaller homolog LTK (leukocyte tyrosine kinase) and the ligands PTN and MK in cancer tissues from patients correlate significantly with worse course and outcome of the disease." (PMID 23267434, 2012). "Based on RT-PCR analysis, PTN mRNA was found in all carcinomas, but there was little or no expression in normal ovaries." (PMID 22496782, 2012). "We also observed a trend to higher PTN levels in CPG5 serum compared to cancer-free and CPG1 groups, although the difference was not statistically significant, which could be potentially attributed to the high sensitivity of the proteomic assay." (PMID 33288843, 2021). "Additionally, the precise mechanisms by which PTN and VEGF-D originating from CAFs contribute to cancer cell behavior have not been fully elucidated." (PMID 38766528, 2024).
neurodegenerative disease (8 papers, 2014 to 2025). A disorder of the central nervous system characterized by gradual and progressive loss of neural tissue and neurologic function. "Pleiotrophin deletion upregulates caspase 6, which is associated with axonal degeneration and neurodegenerative diseases, and the deleterious effects produced can be partially compensated for by the simultaneous induction of the neuroprotective gene MGST3." (PMID 39000460, 2024). "PTN is a cytokine expressed in the human brain, and its expression level was shown to be increased in response to inflammatory triggers that might be caused by neurodegenerative diseases." (PMID 40301248, 2025). "Our review has found PTN participates in the repairment of brain injuries, including hypoxic-ischemic brain injury, preterm white matter injury, traumatic brain injury, and neurodegenerative diseases." (PMID 39829367, 2025). "Our review has found PTN participates in the repairment of brain injuries, including hypoxic-ischemic brain injury, preterm white matter injury, traumatic brain injury, and neurodegenerative diseases, mainly based on animal data and small sample size studies." (PMID 39829367, 2025). "In Central Nervous System (CNS), PTN exerts post-developmental neurotrophic and -protective effects, and additionally has been involved in neurodegenerative diseases and neural disorders." (PMID 25620911, 2014). "PTN actively exerts neuroprotective effects and participates in the repairment of brain injuries, including hypoxic-ischemic brain injury, preterm white matter injury, traumatic brain injury and neurodegenerative diseases." (PMID 39829367, 2025). "PTN has been widely studied in angiogenic, fibrotic and neurodegenerative diseases." (PMID 25617851, 2015). "Pleiotrophin (PTN), a secreted, multifunctional cytokine, is involved in angiogenic, fibrotic and neurodegenerative diseases." (PMID 25617851, 2015).
infection (6 papers, 2011 to 2024). The state of being infected such as from the introduction of a foreign agent such as serum, vaccine, antigenic substance or organism. "Six of these genes were predicted to be involved in host immune response to infection: PTN on BTA4, AP3B1 on BTA10, HSF1on BTA14, SHARPIN on BTA14, TRAF4 on BTA20 and FKBP5 on BTA23." (PMID 26960806, 2016). "First, we developed an adenoviral vector to induce PTN expression in the brain which provided a time window of maximal expression during the two weeks that follow the infection." (PMID 21649894, 2011).
metabolic disorders (3 papers, 2019 to 2024). "Therefore, our objective was to investigate the role of PTN in the morphology and functionality of pancreatic islets, providing new evidence of a new target involved in the pathophysiology of metabolic disorders associated with glucose homeostasis." (PMID 39456743, 2024). "In terms of metainflammation, potentiation of PTN/MK signaling pathways may contribute to control the inflammatory condition associated to metabolic disorders." (PMID 31031625, 2019). "In fact, PTN has been suggested to be a druggable target for metabolic disorders as it is involved in the crosstalk between white and brown adipose tissue regulating thermogenesis, and in the liver accumulation of lipids in high-fat diet-induced obesity." (PMID 39456743, 2024). "As PTN signaling pathway regulates the inflammatory condition related to metabolic disorders, pleiotrophin has been postulated as a promising candidate for CNS and peripheral metabolism crosstalk." (PMID 37484951, 2023). "In this review we summarize the main roles of pleiotrophin in the development and metabolism of key metabolic organs, and how these effects may contribute to the development of metabolic disorders and more precisely, metabolic syndrome." (PMID 37484951, 2023).
neurological disorders (3 papers, 2017 to 2025). "Pleiotrophin (PTN), a cytokine implicated in autoimmune and neurological diseases, is significantly elevated in patients with relapsing-remitting MS (RRMS)." (PMID 41465519, 2025). "Elevated serum levels of pleiotrophin (PTN), a neuroimmunomodulatory cytokine implicated in autoimmune and neurological diseases, have been observed in RRMS patients compared to healthy control subjects (HCS)." (PMID 41465519, 2025). "Evidence strongly suggests that regulation of the PTN and MK signaling pathways may provide new therapeutic opportunities particularly in those neurological disorders characterized by increased PTN and/or MK cerebral levels and neuroinflammation." (PMID 31031625, 2019). "Our results indicate that the regulation of PTN signaling pathways may constitute new therapeutic opportunities particularly in those neurological disorders characterized by increased PTN cerebral levels and neuroinflammation." (PMID 28259175, 2017). "Our results suggest that regulation of the PTN signaling pathways may constitute new therapeutic opportunities particularly in those neurological disorders characterized by increased PTN cerebral levels and neuroinflammation." (PMID 28259175, 2017).
brain disorder (2 papers, 2017 to 2022). A disease affecting the brain or part of the brain. "Interestingly, amphetamine- and cocaine-induced alterations in the striatal phosphoproteome of Ptn−/− mice were similar to those found in PD7–9, suggesting that PTN may protect against neuronal injury in different brain disorders." (PMID 35246557, 2022).
PTN also shares sentences with these, for which no sentence is quoted: colon carcinoma (3 papers); amyloid (2); amyotrophic lateral sclerosis (2); Arthritis (2); bladder cancer (2); Hyperinsulinemia (2); rheumatoid arthritis (2); Sepsis (2); small cell lung carcinoma (2); anaplastic oligodendroglioma (1); atherosclerosis (1); cervical cancer (1); chronic lymphocytic thyroiditis (1); Cognitive impairment (1); dermatitis (1); diabetic nephropathy (1); diffuse midline glioma (1); embryonal carcinoma (1); endometrial carcinoma (1); endotoxemia (1); experimental autoimmune encephalomyelitis (1); familial Mediterranean fever (1); glaucoma (1); Glucose intolerance (1); Graves disease (1); Impaired glucose tolerance (1); inflammation (1); ischemic stroke (1); kidney tumours (1); lung squamous cell carcinoma (1).
A further 23 diseases each share a sentence with PTN in 1 paper.